RNU6-433P (RNA, U6 small nuclear 433, pseudogene)
Gene: Small nuclear RNA gene on chromosome 2 (55,014,418 to 55,014,521, reverse strand). Ensembl gene ENSG00000200086.
Homologues: Orthologues: chimpanzee U6 (100% identical), macaque U6 (91% identical), macaque U6 (88% identical), dog U6 (86% identical), rat LOC120103215 (83% identical), pig U6 (74% identical), rabbit U6 (73% identical), guinea pig U6 (59% identical). Paralogues in human: RNU6-480P (89% identical), RNU6-140P (88% identical), RNU6-16P (88% identical), RNU6-21P (88% identical), RNU6-33P (88% identical), RNU6-46P (88% identical), RNU6-1 (87% identical), RNU6-1026P (87% identical), RNU6-1099P (87% identical), RNU6-1103P (87% identical), RNU6-116P (87% identical), RNU6-1227P (87% identical), and 1286 more.